H2BC20P (H2B clustered histone 20, pseudogene)
Description:
Core component of nucleosome. Nucleosomes wrap and compact DNA into chromatin, limiting DNA accessibility to the cellular machineries which require DNA as a template. Histones thereby play a central role in transcription regulation, DNA repair, DNA replication and chromosomal stability. DNA accessibility is regulated via a complex set of post-translational modifications of histones, also called histone code, and nucleosome remodeling.
Synonyms: H2B/t; HIST2H2BC; LETN; HIST2H2BD
Gene: Transcribed unprocessed pseudogene on chromosome 1 (149,850,193 to 149,850,772, reverse strand). Ensembl gene ENSG00000261716.
Subcellular location: Nucleus; Chromosome
Diseases named in the same sentence as H2BC20P in open-access papers:
H2BC20P is named in the same sentence as 5 diseases in open-access papers, as found by Europe PMC text mining. Sharing a sentence is not in itself a finding about the gene and the disease.
H2BC20P shares sentences with these, for which no sentence is quoted: cancer (2 papers); liver cancer (1); lung carcinoma (1); prostate carcinoma (1); tumor (1).